IFNG (interferon gamma)
Diseases named in the same sentence as IFNG in open-access papers (continued):
Sharing a sentence is not in itself a finding about the gene and the disease.
tumor (continued). "Lymphocytes secrete interferon‐gamma (IFN‐γ) and tumor necrosis factor-alpha (TNF-α) which are very important for inducing cytotoxic cell death and inhibiting tumor proliferation and tumor migration." (PMID 38910770, 2024). "As shown by CyTOF analysis, there was a phenotype change in about half of the tumor cells—characterized by upregulation of both anti-inflammatory (PDL1) and inflammatory (H2Db) surface markers in the group treated with IFNγ." (PMID 38636457, 2024). "The combination of radiotherapy and oral vancomycin enhanced antigen presentation in tumors and regional lymph nodes, elevated interferon-gamma (IFN-γ) levels, and increased CD8+ T cell activity within the tumor microenvironment (TME)." (PMID 39858295, 2024). "Along these lines, restimulation of CK-exposed CD8+ cells yielded reduced induction of IFNγ and TNFα, two signature effector cytokines of cytotoxic CD8+ cells involved in tumor clearance." (PMID 38570506, 2024). "M1 macrophages, activated through the classical pathway by interferon-gamma (IFN-γ), are typically present in the tumor microenvironment (TME) during early stages of acute inflammation, promoting an anti-tumoral inflammatory response." (PMID 38338162, 2024). "CD4 T-cells produce interferon gamma (IFN-γ), a cytokine essential in tissue homeostasis, immune and inflammatory responses, and tumor immunosurveillance." (PMID 39156997, 2024). "Tumor cells can secrete numerous pro-inflammatory factors such as TNF-α, interferon-gamma (IFN-γ), IL-1 and IL-6, and parathyroid hormone-related protein (PTHrP) that can trigger cancer cachexia." (PMID 39697630, 2024). "We observed the production of IFNγ in 12 wells from 6 cases, including 11 wells from 5 cases of MGMT-H tumors and 1 well from 1 case of MGMT-L tumor." (PMID 38288307, 2024). "We observed that interferon-alpha (IFN-α) and interferon-gamma (IFN-γ) very strongly induced the activation of the STAT1 protein, whereas IL-6 and IFN-α activated STAT3 and IL-4 activated STAT6 in all examined tumor cell lines." (PMID 38396958, 2024). "Taken together, our study shows that the antitumor effect of combination Ad-E and αPD-1 mAb treatment depends on the accumulation of tumor-infiltrating CD3+ T cells, NK cells, IFNγ+CD8+ T cells by gut microbiota." (PMID 39251538, 2024). "These pathways include releasing perforin, granzyme, interferon‐gamma (IFN‐γ), tumor necrosis factor‐alpha (TNF‐α), and other factors that initiate the tumor cell apoptosis pathway." (PMID 38234174, 2024). "The effect was correlated with an increase in IFNγ and TNFα production from splenocytes, a decrease in proliferation Ki-67 and micro vascularization CD31 levels, and an increase in tumor necrosis." (PMID 38803496, 2024). "The release of IFNγ by CD8+ T cells has been found to down-regulate the expression of SLC7A11, thereby restricting cystine uptake by tumor cells and promoting tumor cell lipid peroxidation and ferroptosis." (PMID 38655266, 2024). "The activation of STING signaling by F. nucleatum resulted in increased PD-L1 expression and accumulation of interferon-gamma and subsequently CD8 + tumor-infiltrating lymphocytes, leading to tumor inhibition." (PMID 38273292, 2024). "In the tumor microenvironment, arachidonic acid, in combination with IFNγ produced by CD8+ T cells, induces tumor ferroptosis in an ACSL4-dependent manner." (PMID 39402302, 2024). "The three TCR-transduced human T cells also recognized NY-ESO-1+A2+ human tumor lines to different degree, with TCR-ESO-expressing T cells secreting the highest amount of IFNγ upon tumor cell recognition." (PMID 39776913, 2024). "Analysis of the MDMs demonstrated that IFNG neutralization diminished induction of CXCL9, CXCL10 and CXCL11 gene expression in MDMs in both tumor model systems." (PMID 39414902, 2024). "Interferon-gamma (IFN-γ), a critical cytokine for tumor cell recognition and elimination by CD8+ T cells, was measured in the co-culture supernatants." (PMID 39329721, 2024).
tumor (continued). "As for an impact on immune signaling, SRSF10 has recently been reported to inhibit the IFNα/IFNγ signaling pathway and suppress CD8+T cell infiltration, while its knockdown enhanced the anti-PD-L1-mediated anti-tumor activity." (PMID 38753413, 2024). "They enhance the anti-tumor immune response by releasing cytokines, such as tumor necrosis factor-alpha (TNF-α) and interferon-gamma (IFN-γ)." (PMID 38720149, 2024). "We have demonstrated that NAD+ metabolism drives IFNγ-induced PD-L1 checkpoint expression via TET1 and promotes tumor immune evasion." (PMID 38177099, 2024). "CD8+ T cells and activated CD8+ (CD8+IFNγ+) T cells in spleens and tumors were determined by flow cytometry in order to investigate whether the promotion of TAMs and the inhibition of immunosuppressive factors could induce the recruitment and the activation of tumor-specific T cells in tumors." (PMID 38203835, 2024). "Mice fed a KD showed increased cytokine production (IFNγ, TNF, and IL-2) and greater tumor-reactive CD8+ T-cell cytotoxicity." (PMID 38462638, 2024). "IFNγ released by immunotherapy-activated CD8+ T cells downregulates SLC3A2 and SLC7A11 expression, enhancing ferroptosis-specific lipid peroxidation in tumor cells." (PMID 39402302, 2024). "For example, SG enhances tumor sensitivity to anti-PD-1 therapy by recruiting natural killer (NK) or CD8+ T cells to infiltrate the TME, where they secrete interferon-gamma and granzyme B to mediate tumor cell cytotoxicity." (PMID 39555080, 2024). "To further validate the robust IFNγ production by attIL12-TILs, we set up an in vitro model by coculturing SA127 or SA174 tumor cells with autologous control or attIL12-TILs at a tumor cell:T cell ratio of 4:1 for 24 hours." (PMID 39574893, 2024). "Tumor tissues from these mice showed increased mature dendritic, CD4+ T, and CD8+ T cells and pro-inflammatory cytokines (IFNγ and TNFα) and decreased regulatory T cells, and the expression of tumor cell proliferation markers (Ki67 and CD31) was downregulated." (PMID 38323311, 2024). "In this regard, IFNγ produced by CAR-T cells upregulates ICAM-1 on tumor cells and strengthens CAR-T and tumor cell interaction, facilitating tumor killing in solid tumors." (PMID 38779672, 2024). "Consistent with the cytotoxic potential of UniCAR T-cells obtained, the secretion of Interferon gamma (IFNγ), Interleukin 2 (IL-2) and Tumor Necrosis Factor alpha (TNFα) increase in a TM dose-dependent manner in both FAP+ tumor models and for all TMs." (PMID 39000348, 2024). "IFNγ production was lowest in T cells from CD83OE tumor mice, suggesting that additional T-cell interactions in vivo likely modulate tumor-derived production of cytokines." (PMID 39601621, 2024). "This platform increased IL-12, IFNγ, and CD8+ T cell infiltration and reduced Tregs within the injected tumor." (PMID 38803496, 2024). "PDT-treated cancer cell pulsed DC vaccine showed superior tumor suppression to PDT-treated whole-cell vaccine, which was correlated with increased IFNγ-producing CD8+ T cells and decreased Tregs." (PMID 38646546, 2024). "The ratio of tumor-infiltrating CD8+/Foxp3+CD25+ Tregs and the frequency of cytotoxic IFNγ+ CD8+ cells were significantly higher in the iPSC/RT subgroup, suggesting a predominance of immune system activation over suppression within the tumor microenvironment." (PMID 38821980, 2024). "Cytokines play a crucial role as mediators in the TME, with cytokines involved in adaptive immune responses (e.g., IFNγ, IL-2, IL-12, and TNF) positively impacting anti-tumor immunity." (PMID 38928150, 2024). "Strikingly, CBX3 deletion heightened CRC cells sensitivity to IFNγ, which ultimately enhanced their chemosensitivity under IFNγ stimulation in vitro with CRC cells and in vivo with a syngeneic mouse tumor model." (PMID 38684864, 2024).
tumor (continued). "Collectively, elevated GBP5 expression in T cells potentially promotes T cell activation and infiltration, while simultaneously reducing the release of tumor-killing molecules, as evidenced by the downregulation of GZMB and IFNγ transcription in Jurkat cells." (PMID 38817865, 2024). "This increase is induced by interferon-gamma (IFN-γ), which is secreted by tumor-infiltrating lymphocytes and cancer cells within the tumor, along with other inflammatory mediators." (PMID 38474186, 2024). "TMPyP4 therapy significantly increased the percentages of IFNγ+, TNFα+, and Perforin+ CD8+ T cells in the tumor microenvironment compared to control groups." (PMID 39528472, 2024). "The cytokines IFNG and IFNA can exert both pro-tumorigenic and anti-tumorigenic effects depending on their concentrations and the tumor microenvironment." (PMID 38287309, 2024). "To identify miRNA that are dysregulated during pro-tumour and anti-tumour TAM polarisation, we performed small RNA sequencing on in vitro SKOV-3 generated TAMs ± LPS/IFNγ and autologous monocytes from four donors." (PMID 39763667, 2024). "KD of iRhom1 via the NPs led to a significant improvement in tumor immune microenvironment as evident from increases in both the total numbers of CD8+ T cells and the numbers of functional (IFNγ+ or GzmB+) CD8+ T cells." (PMID 38177179, 2024). "In the tumor microenvironment (TME), IFNγ stimulates cancer cells to induce EMT, which can contribute to immunosuppression and to resistance to ICBs." (PMID 38802348, 2024). "Consistent with the IF assay findings, the IFNγ secretion by orthotopic tumor tissues was dose‐dependently increased by IL12, and the highest level of IFNγ secretion was observed in the JQ1+IL12‐L group." (PMID 38417121, 2024). "Conversely, IL-10 can hinder antigen presentation and suppress interferon gamma (IFN-γ), thereby potentially dampening anti-tumor immunity." (PMID 39202777, 2024). "As expected, atezolizumab efficiently blocked both basal and IFNγ-induced PDL1 levels, which abrogated the tumor cell targeting by NExT." (PMID 38730475, 2024). "TAGLN2 overexpression significantly prevented the PARP cleavage in cells induced by Dox, VP16, and IFNγ, establishing that TAGLN2 enhances tumor chemoradio resistance in vitro." (PMID 39168971, 2024). "Fifty percent of patients who had survived beyond 6 months showed an increase in IFNγ spots during treatment compared with baseline, meaning that treatment with MVX-ONCO-1 can trigger a tumor-specific immune response from PBMCs in this patient population." (PMID 39041242, 2024). "In the adaptive immune response, TGF-β regulates the production of a variety of cytolytic genes including granzyme A, granzyme B, IFNγ, and FAS ligands, which impair the anti-tumor activity of CD8 + T cells, ultimately leading to pro-tumor TME." (PMID 39065562, 2024). "IL-12 further activates iNKT to secrete IFNγ which can activate multiple cell types such as NK and CD8+ T-cells to mediate tumor killing." (PMID 39170618, 2024). "IFNγ signaling also promotes MET activation and induce immune checkpoints via enhanced MET-STAT4-PD-L1 axis in tumor cells, providing tumor cells with immune evasion mechanism." (PMID 38916448, 2024). "Chen’s group also demonstrated that EGFR-CAR NK-92 cells(second-generation CAR) increased cytolysis and IFNγ production in breast cancer cell lines MDA-MB-231, MDA-MB-468, and MCF-7 (in vitro), and reduced tumor growth in tumor-bearing mice (in vivo)." (PMID 38245520, 2024). "Following the co-culture, we measured the levels of Tumor Necrosis Factor-α (TNFα), Interferon-γ (IFNγ) and Interleukin-2 (IL2), important for T-cell anti-tumor activity and proliferation." (PMID 39512355, 2024). "In this line, our Consortium is evaluating the combination of CAR-T cells with other approaches targeting IFNγ and other cytokines to promote CAR-T/tumor cell IS." (PMID 38779672, 2024).
tumor (continued). "CD8+ TIL polyfunctionality was predicated on coordinate CD8+ TIL responder intracellular expression of IFNγ, TNFα, and IL2 as determined by flow cytometry after a 5 h in vitro stimulation with either tumor cells or PVECs." (PMID 39066414, 2024). "Gene expression profiling of CR705Parp7KO compared with CR705Cas9 tumours in C57BL/6 mice revealed increases in IFN-I and IFNγ signalling as well as other immune signalling pathways." (PMID 39867896, 2024). "By promoting IFNγ signal transduction, STUB1 inhibition makes tumor cells more vulnerable to T cells." (PMID 39223632, 2024). "CD8+ T cells, pivotal players in antitumor immunity, secrete cytokines such as IL-2, IL-12, and IFNγ within the TME, enhancing their ability to target and eliminate tumor cells." (PMID 39273090, 2024). "Previous studies have demonstrated the requirement of IFNγ and IL1/TNF cytokines for tumor NOS2/COX2 expression, in which correlations between tumor NOS2 and CD8 expressions were observed at the tumor stroma interface." (PMID 39356141, 2024). "Consistently, OT-I T cells co-cultured with thimerosal-treated tumor cells also upregulated the expression levels of activation markers CD25, CD69, and effector molecules such as intracellular Granzyme B (GZMB) and IFNγ." (PMID 39349845, 2024). "The incorporation of IL-12 into the SV vector enhanced the therapeutic effect by inducing IFNγ secretion from NK cells, which was shown to upregulate the expression of MHC class II on peritoneal macrophages promoting an M1 anti-tumor effect." (PMID 38474178, 2024). "Treatment with tretinoin induces a robust anti-tumor CD8+ T cell response, increasing proliferation, expression of effector molecules IFNγ, granzyme B and perforin, as well as activation and cell migration markers." (PMID 38350880, 2024). "Tumor-specific T cells highly expressed CD27, IFNG, GZMB and CXCL13 and secreted more effector cytokines for tumor cell killing, as validated experimentally." (PMID 39033098, 2024). "Comparing changes in absolute cytokine levels for IFNγ and the IFNγ-inducible cytokines CXCL9 and CXCL10 to the tumor-related cytokines EGF, HGF and VEGF highlights the strong treatment related effects for IFNγ-pathway related cytokines." (PMID 38454126, 2024). "In the context of serial co-cultures with OVCAR-3 or MCF7 tumour cells, FOXO1 overexpression led to a significant increase in the recovery of CD8+ and CD4+ CAR T cells and similar levels of IFNγ and TNF production compared with control CAR T cells." (PMID 38600376, 2024). "In particular, compared to the Ctrl group, CD8+IFNγ+ T cells were significantly higher in the IASNDS@gel treatment group, suggesting a more pronounced anti-tumor immune response within the GBM." (PMID 38762500, 2024). "The 16-biomarker panels were divided into three categories of inflammatory markers (SAA, CRP, NLR, PLR, and LDH), TH1/TH2 cytokines (IL-2, IL-4, IL-5, IL-6, IL-8, IL-10, IFNγ, TNF, and GM-CSF), and HCC tumor markers (AFP and PIVKA-II)." (PMID 38409200, 2024). "To investigate how IFNγ and TGFβ affect CCKAR and collagen expression in the presence of TILs, we cocultured tumor cells with autologous control TILs or attIL12-TILs with or without additional IFNγ, TGFβ, or their neutralizing antibodies." (PMID 39574893, 2024). "For instance, the secretion of interferon gamma (IFN-γ) by CD8+ T cells has been shown to down-regulate the expression of SLC3A2 and SLC7A11 in tumor cells, leading to a disruption in cystine uptake." (PMID 39040097, 2024). "MPE-Tem and MPE-Tcm secreted more IFNγ, TNFα, and IL-2 compared to paired MPE-TemRA and MPE-Tnaive, which were used to kill tumor cells." (PMID 39372862, 2024). "Functional studies showed that BTLA blockade increased the percentage of IFNγ + NK-cells and IFNγ + CD8 + T-cells, decreased the secretion of IL-10 by CLL B-cells, and increased tumor cell lysis." (PMID 38233898, 2024).
tumor (continued). "Meanwhile, IFNγ can also suppress VEGF mRNA transcript levels in endothelial cells, thereby exerting an anti-tumor angiogenesis effect." (PMID 39149649, 2024). "In the tumor microenvironment (TME), IFNγ is produced predominantly by tumor-infiltrating lymphocytes (TILs), particularly by activated CD8 cytotoxic T cells." (PMID 39123403, 2024). "Conditioned media from tumor organoids #2 and H1975 cells significantly suppressed CD3+CD8+IFNγ+ T cells." (PMID 38528665, 2024). "cDC1 reprogramming synergized with anti-PD-1 or anti-CTLA-4 treatment leading to increased CR in B16 and B2905, which also resulted in expansion of tumor antigen-specific IFNγ+CD8+ and IFNγ+CD4+ T cells in peripheral blood." (PMID 39236156, 2024). "LILRB4 blockade restored IL-2 production in HDVax-induced cells and enhanced their expression of IFNγ/TNF and CD40L in both T3 and F244 tumour models." (PMID 39048822, 2024). "Studies have found that IFNG, CXCL9, and CD274 expression in tumor specimens correlate to stronger immunotherapy responses." (PMID 38265267, 2024). "We recently demonstrated significant correlations between tumor NOS2 and COX2 expression and both stroma-restricted CD8+ T effector cells and secreted IFNγ in these tumors." (PMID 39356141, 2024). "IL6 produced by cancer-associated fibroblasts (CAF) augmented the production of proinflammatory cytokines such as IFNγ and IL17A by tumor-infiltrating T cells." (PMID 38819641, 2024). "Consistent with bulk tumor transcriptional profiles, GSEA in malignant cells revealed increased IFNα and IFNγ signatures coupled with decreased glycolysis signatures in high-heteroplasmy tumors, which is not observed in vitro before implantation." (PMID 38286828, 2024). "The administration of Ox-RtH in the mild-treated groups resulted in significantly higher production of IFNγ and IL10 at the 3rd and 5th week after challenge with B16F10 cells, when compared with the control tumor-bearing group." (PMID 39452870, 2024). "A small SC134-TCB–induced increase in IFNγ and IL2 was detectable, potentially already reflecting tumor target–mediated cytokine production." (PMID 39186309, 2024). "These tumor-specific upregulated genes included inhibitory receptors, such as ENTPD-1 49 and PDCD1, as well as effector molecules, such as GZMK and IFNG, all involved in antitumor activity." (PMID 38948071, 2024). "We show that PRMT3 expression is induced by ICB-activated T cells via an interferon-gamma (IFNγ)-STAT1 signaling pathway, and higher PRMT3 expression levels correlate with reduced numbers of tumor-infiltrating CD8+ T cells and poorer response to ICB." (PMID 39256398, 2024). "M1 macrophages are polarized by lipopolysaccharide (LPS), interferon-gamma (IFN-γ), or tumor necrosis factor (TNF), leading to the secretion of pro-inflammatory cytokines and the ability to eliminate microorganisms and tumor cells." (PMID 38894865, 2024). "Tumor phenotype conversion was dependent on a CD8+ T cell phenotype with ability to divide rapidly (memory-like) and secrete IFNγ (effector-like), suggesting this as a design criterion/goal for T cell therapies as well as a matching patient selection metric." (PMID 38636457, 2024). "Neutralizing antibodies against IFNγ or granzyme B suppressed CTL cytotoxicity and reduced apoptotic markers in tumor cells." (PMID 39292167, 2024). "This includes the secretion of Interferon-gamma (IFN-γ), GZMB, and other factors, ultimately leading to tumor cell lysis." (PMID 39519376, 2024). "CAR-T cells also release cytokines, such as interferon-gamma (IFN-γ) and tumor necrosis factor-alpha (TNF-α), which subsequently activate the host immune system to inhibit tumor growth and metastasis." (PMID 38146589, 2024). "It has been demonstrated that interferon gamma released by CD8+ T cells inhibits system xc-glutamate-cystine antiporter, limiting the cystine uptake by tumor cells, thereby enhancing tumor cell lipid peroxidation and inducing iron-dependent cell death." (PMID 38602575, 2024).